MDM2 (MDM2 proto-oncogene)
Diseases named in the same sentence as MDM2 in open-access papers (continued):
Sharing a sentence is not in itself a finding about the gene and the disease.
undifferentiated pleomorphic sarcoma (9 papers, 2019 to 2025). An undifferentiated soft tissue sarcoma characterized by the presence of a pleomorphic malignant cellular infiltrate. "Interestingly, undifferentiated pleomorphic sarcomas (UPS) of the heart have recently been suggested to represent the cardiac analog of ISA due to morphological overlap and high prevalence of MDM2 amplifications in both neoplasms." (PMID 34312479, 2021).
fibrosarcoma (8 papers, 2004 to 2026). A malignant mesenchymal fibroblastic neoplasm affecting the soft tissue and bone. "Low-grade fibrosarcoma reveals MDM2, CDK4, and SATB2 positivity." (PMID 37602060, 2023).
meningioma (8 papers, 2015 to 2024). A generally slow growing tumor attached to the dura mater. "Intratumor copy number heterogeneity was also observed in one high-grade meningioma affecting the MDM2 proto-oncogene." (PMID 35701666, 2022). "Further studies are needed to improve our understanding of MDM2 heterogeneity and its clinical impact in meningioma patients." (PMID 35701666, 2022). "Amplification of the MDM2 is a rare genomic alteration in high-grade meningioma and it is considered to drive malignant progression." (PMID 35701666, 2022). "Intratumor heterogeneity of MDM2 could potentially have implications when evaluating the clinical outcome of meningioma patients, for instance in clinical trials of targeted therapeutics with MDM2 inhibitors." (PMID 35701666, 2022).
mucosal melanoma (8 papers, 2018 to 2025). A melanoma that arises from a mucosal site. "Cross-species comparison of regions with significant copy number gain revealed that the mouse double minute 2 homolog (MDM2) gene is focally amplified in human and canine mucosal melanomas." (PMID 30664638, 2019). "The combined inhibition of CDK4, MDM2 and TERT presents a promising therapeutic strategy for mucosal melanoma, as amplifications of these three genes frequently co-occur in this cancer subtype." (PMID 39598629, 2024). "At present, some studies have found that mutations that activate SF3B1 and KIT, the deletion of CDKN2A, PTEN, or SPRED1, and the amplification of CDK4, TERT, KIT, MDM2, or CCND1 are common in mucosal melanoma." (PMID 38065883, 2023). "All but one of the eight tumors in this study with translocations between 5p and 12p, usually resulting in amplifications of MDM2/CDK4 and TERT, were oral mucosal melanomas and of East Asian ancestry." (PMID 31320640, 2019).
Obesity (8 papers, 2009 to 2025). Accumulation of substantial excess body fat. "Given that the expression of several genes involved in adipose tissue homeostasis is known to change in response to metabolic challenges and obesity development, we examined the levels of Mdm2 mRNA in the white adipose tissue (WAT) of diet-induced obese mice and genetically obese, ob/ob, mice." (PMID 34750429, 2021). "This study identifies murine double minute 2 (MDM2) as a novel E3 ubiquitin ligase that targets apolipoprotein B (ApoB) for proteasomal degradation, leading to impaired TG‐VLDL secretion and hepatic TG accumulation in obesity." (PMID 35524581, 2022).
prostate tumors (8 papers, 2008 to 2025). "For example, MDM2 was shown to promote AR protein degradation, and thus MDM2 expression is predicted to attenuate AR-dependent transcription in prostate tumor cells." (PMID 27365400, 2016). "As our study revealed no significant changes in the allelic distribution between PCa patients and men without any malignancy, it is unlikely that the Mdm2 SNP309 plays an important role for increased Mdm2 expression in prostate tumours." (PMID 18577987, 2008). "Assuming that MDM2 promotes AR protein degradation/turnover, our results suggest that this process is required for normal ligand-dependent AR transcriptional activity in prostate tumor cells." (PMID 27365400, 2016). "Therefore, a subset of prostate tumours with Mdm2 overexpression might evolve as a suitable target for the application of selective Mdm2 inhibitors in the future." (PMID 18577987, 2008). "We speculate that the discordant effects on AR-mediated transcription observed between the siRNA luciferase screen and reported AR coregulator functions of MDM2, RNF6, and USP10 in prostate tumor cells are due to differences in prostate tumor cell lines and reporter vectors." (PMID 27365400, 2016). "However, cells transfected with validated MDM2 siRNAs failed to potentiate AR transcriptional activity in LNCaP prostate tumor cells." (PMID 27365400, 2016).
undifferentiated sarcoma (8 papers, 2013 to 2022). "Further studies are warranted to better understand the nosologic position of MDM2-amplified undifferentiated sarcoma at the peripheral sites." (PMID 30018380, 2018). "MDM2 amplification was also present in some adjacent bland adipose tissue, and also in the tumor recurrence as a pleomorphic undifferentiated sarcoma." (PMID 26987706, 2016).
atherosclerosis (7 papers, 2018 to 2025). A disease characterized by the build-up of fatty material and calcium deposition in the arterial wall resulting in partial or complete occlusion of the arterial lumen. "Dysregulated MDM2 is implicated in cardiovascular impairments as well such as atherosclerosis." (PMID 40040717, 2025). "In endothelial dysfunction and atherosclerosis associated with APS-related features, overexpression of MDM2 exacerbates mitochondrial damage and activates TLR9/NF-κB and NLRP3/caspase-1 pathways." (PMID 40040717, 2025). "The DNA damage kinase ATM is an upstream regulator of MDM2, and it does modulate the endothelial function, playing a role in atherosclerosis and angiogenesis." (PMID 31921839, 2019). "With these newly acquired mechanistic insights, we propose that targeting the MDM2-RXRβ regulatory axis could represent a novel strategy for human atherosclerosis therapy." (PMID 35628577, 2022). "In this pathway, under conditions that lead to atherosclerosis, the expression of MDM2 is induced, and MDM2 functions as a ubiquitin E3 ligase to target RXRβ for degradation, which contributes to mitochondrial damage and subsequently mitochondrial-related inflammation in atherosclerosis." (PMID 35628577, 2022). "This time we examined whether blockade of MDM2 activity by JNJ-165 could result in the prevention of atherosclerosis in atherosclerotic mice." (PMID 35628577, 2022). "Several pieces of evidence converge to suggest that crosstalk between MDM2 and elements of the renin-angiotensin-aldosterone system could support atherosclerosis by modulating smooth muscle hypertrophy." (PMID 31921839, 2019). "These actions of MDM2 would ultimately facilitate atherosclerosis." (PMID 31921839, 2019). "Therefore, based on our previous studies, we were encouraged to investigate whether MDM2 acts as an E3 ligase to regulate the stabilization of RXRβ and further illustrate the function of MDM2 in atherosclerosis." (PMID 35628577, 2022). "Furthermore, the present study for the first time shows that pharmacological inhibition of MDM2 (which increased protein expression of RXRβ) attenuates the development of atherosclerosis and reverses mitochondrial damage and the related inflammation in this process." (PMID 35628577, 2022). "Moreover, the in vivo experiment in the present study for the first time showed that MDM2 inhibitor JNJ-165 alleviated the development of atherosclerosis and reversed mitochondrial damage and related inflammation in this process, along with the increased RXRβ protein expression in the aorta of mice." (PMID 35628577, 2022). "Additionally, our results identify MDM2 as a potent target for atherosclerosis therapy." (PMID 35628577, 2022). "Therefore, our study uncovers a previously unknown ubiquitination pathway and suggests MDM2-mediated RXRβ ubiquitination as a new therapeutic target in atherosclerosis." (PMID 35628577, 2022).
atherosclerosis (continued). "Additionally, we identified 4 new MMVD stage B2 targets (MDM2, ROCK1, RIPK1, and SNAP23) that have been studied in many cardiovascular diseases in human medicine, such as chronic heart failure, atherosclerosis, and diabetic cardiomyopathy." (PMID 38087280, 2023).
cardiac hypertrophy (7 papers, 2016 to 2025). "Contrary to the vascular protective effect of MDM2 inhibitors, it is reported that cardiac-specific ablation of MDM2 leads to broad mitochondrial deficiency and reduced expression of MDM2 in the cardiomyocytes may facilitate cardiomyocyte hypertrophy and cardiac hypertrophy." (PMID 35628577, 2022). "Cardiomyocytes-specific deletion of MDM2 lead to spontaneous concentric hypertrophy and cardiac dysfunction and early mortality." (PMID 31921839, 2019). "Together these data support the idea that reduced expression of MDM2 may facilitate cardiomyocyte hypertrophy and cardiac hypertrophy." (PMID 31921839, 2019). "However, the mechanistic details of MDM2 inhibiting particularly, the cardiac hypertrophy, remains unsettled." (PMID 30186311, 2018). "MDM2 thus having a dual function of being antiapoptotic as well as of preventing hypertrophy in cardiomyocytes advocates the idea of MDM2 serving as a novel cardiac gene therapy target to downregulate both apoptosis and pathologic cardiac hypertrophy." (PMID 30186311, 2018). "The interaction between MDM2 and TCAP is known to be important for cardiac hypertrophy, it was also shown that TCAP controls secretion of MSTN." (PMID 32928103, 2020). "In this review, we have mainly compiled the TRAF superfamily of E3 ligases and few DUBs proteins with other well-documented E3 ligases such as MDM2, MuRF-1, Atrogin-I, and TRIM 32 that are specific to myocardial hypertrophy." (PMID 30186311, 2018). "Since Mdm2 inhibits cardiac hypertrophy, whereas Akt promotes this process, the existence of a negative feedback loop has been postulated, enabling Mdm2 to restrain Akt action." (PMID 29267372, 2017).
COVID-19 (7 papers, 2020 to 2024). A disease caused by infection with severe acute respiratory syndrome coronavirus 2. "Treatment based on MDM2 inhibitors delivered by EVs should be considered for further evaluation for COVID-19 patients." (PMID 35668941, 2022). "Collectively, these data highlight the possibility that dysregulated MDM2 activity could be a risk factor for SARS-CoV-2 infection and COVID-19 pathogenicity." (PMID 37632105, 2023). "Further bioinformatic analysis revealed 8 core targets (EGFR, AR, ESR1, MAPK8, MDM2, EZH2, ERBB2 and MAPT) in the VitD-COVID-19-osteoporosis network." (PMID 36307516, 2022). "At present, it is not known how a non-cancer SARS-CoV-2-infected cell could respond to MDM2 inhibitors, but their use has been recently proposed as a possible strategy for COVID-19 patients." (PMID 36582523, 2022).
embryonal carcinoma (7 papers, 2011 to 2021). A non-seminomatous malignant germ cell tumor characterized by the presence of large germ cells with abundant cytoplasm resembling epithelial cells, geographic necrosis, high mitotic activity, and pseudoglandular and pseudopapillary structures formation. "All embryonal carcinomas were homogeneously positive for MDM2, whereas the other histologic components were heterogeneous." (PMID 34068019, 2021). "Only one patient (1/12) with embryonal carcinomas showed MDM2 amplification." (PMID 34068019, 2021).
Hepatic steatosis (7 papers, 2020 to 2025). Steatosis is a term used to denote lipid accumulation within hepatocytes. "Our RibosomeR analysis further suggests the functional relevance of tissue-specific heterogeneity, exemplified by the involvement of RACK1 and MDM2 in adipogenesis and fatty liver disease." (PMID 39086661, 2024). "Chronic HFD exposure in Mdm2-AKI mice apparently induced severe hepatic steatosis, including massive accumulations of large lipid droplets and increasing the ballooning degeneration of liver cells." (PMID 35747386, 2022). "Both the obese mouse models exhibited hepatic steatosis, accompanied by elevated hepatic MDM2 protein levels when compared with their corresponding standard chow (STC)‐fed controls and lean (db/+) controls." (PMID 35524581, 2022). "Hepatocyte‐specific deletion of MDM2 protects against high‐fat high‐cholesterol diet‐induced hepatic steatosis and inflammation, accompanied by a significant elevation in TG‐VLDL secretion." (PMID 35524581, 2022). "A recent study demonstrated that MDM2 haploinsufficient in adipocytes induced overt obesity, glucose intolerance, and hepatic steatosis through a novel interplay with the transcriptional cofactors MORC Family CW-Type Zinc Finger 2 (MORC2) and LIPIN1." (PMID 35747386, 2022). "MDM2 inactivation alleviates hepatic steatosis, inflammation, and fibrosis in different mouse models of MAFLD." (PMID 35524581, 2022). "Meanwhile, chronic high-fat diet (HFD) exposure caused obvious epididymal white adipose tissue (eWAT) dysfunction, such as senescence, apoptosis, and chronic inflammation, thereby leading to hepatic steatosis in Mdm2-AKI mice." (PMID 35747386, 2022). "Here, adipocyte-specific MDM2 knock-in mice by adiponectin promoter displayed decreased energy expenditure and increased body weight, insulin resistance, and hepatic steatosis." (PMID 35747386, 2022). "Here, we substantiate this notion further by showing that haploinsufficiency of MDM2 in adipose tissue leads to marked increase in adipose tissue mass, glucose intolerance and hepatic steatosis in young mice." (PMID 34750429, 2021). "Notably, RACK1 regulates adipogenesis, while MDM2 promotes the onset of fatty liver disease, both relevant to adipose tissue function." (PMID 39086661, 2024). "In addition to genetic approach, we employed the Nutlin‐3a to block MDM2‐ApoB interaction, and showed that this pharmacological approach prevents hepatic steatosis and inflammation." (PMID 35524581, 2022). "Furthermore, STEAP4 restoration in eWAT of Mdm2-AKI mice improved MDM2-induced metabolic disorder, including adipocyte dysfunction, insulin resistance, and hepatic steatosis." (PMID 35747386, 2022). "Collectively, these data render it possible that reduced levels of adipose MDM2 may regulate hepatic steatosis through impaired desaturation and secretion of the C16 and C18 NEFAs." (PMID 34750429, 2021). "A recent study documented that hyperhomocysteinemia promoted Mdm2-mediated ubiquitination of HSF1 to activate hepatic NLRP3 inflammasome, thus leading to hepatic steatosis." (PMID 39277582, 2024). "Under obese conditions, hepatic MDM2 overexpression leads to proteasomal degradation of ApoB, thereby lowering TG‐VLDL output, resulting in hepatic steatosis, oxidative stress, and inflammation." (PMID 35524581, 2022). "Summary, the MDM2-STEAP4 axis in eWAT plays an important role in maintaining healthy adipose tissue function and improving hepatic steatosis." (PMID 35747386, 2022). "After 16 weeks of dietary treatment, under STC feeding hepatic lipid content of H‐MDM2‐KO mice was unchanged from that of WT controls, but liver‐specific deletion of MDM2 prevented HFHC diet‐induced hepatic steatosis." (PMID 35524581, 2022). "It was more interesting that Mdm2-AKI mice on a HFD exhibited exacerbated eWAT dysfunction, such as increased cellular senescence, apoptosis, and inflammation, thereby aggravating HFD-induced hepatic steatosis and insulin resistance." (PMID 35747386, 2022).
Hepatic steatosis (continued). "Finally, STEAP4 restoration in eWAT of Mdm2-AKI mice on a HFD rescued MDM2-induced adipose dysfunction, insulin resistance, and hepatic steatosis." (PMID 35747386, 2022). "Furthermore, under HFD feeding condition, MDM2 overexpression induced eWAT dysfunction such as cellular senescence, apoptosis, and inflammation, through ubiquitin-mediated STEAP4 degradation, eventually, exacerbating hepatic steatosis and insulin resistance." (PMID 35747386, 2022).